CFI (complement factor I)
Description:
Trypsin-like serine protease that plays an essential role in regulating the immune response by controlling all complement pathways. Inhibits these pathways by cleaving three peptide bonds in the alpha-chain of C3b and two bonds in the alpha-chain of C4b thereby inactivating these proteins. Essential cofactors for these reactions include factor H and C4BP in the fluid phase and membrane cofactor protein/CD46 and CR1 on cell surfaces. The presence of these cofactors on healthy cells allows degradation of deposited C3b by CFI in order to prevent undesired complement activation, while in apoptotic cells or microbes, the absence of such cofactors leads to C3b-mediated complement activation and subsequent opsonization.
Synonyms: IF; FI; C3b-INA; C3bINA; KAF; AHUS3; ARMD13
Tractability: Antibody: UniProt places it where antibodies can reach, with high confidence; its Gene Ontology location is reachable by antibodies, with high confidence; UniProt predicts a signal peptide or a membrane-spanning region. PROTAC: its protein half-life has been measured.
Gene: Protein-coding gene on chromosome 4 (109,731,008 to 109,802,195, reverse strand). Ensembl gene ENSG00000205403.
Subcellular location: Secreted, extracellular space; Secreted
Pathways (Reactome):
Immune System: Regulation of Complement cascade
Gene Ontology:
Molecular function: protein binding; serine-type endopeptidase activity; serine-type peptidase activity
Biological process: protein processing; complement activation; proteolysis
Cellular component: extracellular exosome; extracellular region; membrane
Genetic constraint (gnomAD): Loss-of-function variants: 50 observed, 58.81 expected, observed/expected ratio (o/e) 0.85, 90% interval 0.68 to 1.08. The upper end of that interval is the gene's LOEUF score, 1.08, which puts it in group 4 of 6, group 1 being the genes least tolerant of losing a copy. Missense variants: 571 observed, 589.67 expected, observed/expected ratio (o/e) 0.97, 90% interval 0.9 to 1.04. Synonymous variants: 204 observed, 198.82 expected, observed/expected ratio (o/e) 1.03, 90% interval 0.92 to 1.15.
Gene-disease validity (ClinGen):
ClinGen rates the evidence that CFI causes each of these diseases.
atypical hemolytic-uremic syndrome (autosomal dominant): Definitive. A rare, genetic thrombotic microangiopathy due to dysregulation of the alternative complement pathway and characterized by the triad of hemolytic anemia, thrombocytopenia, and acute renal dysfunction.
C3 glomerulonephritis (autosomal dominant): Moderate. Glomerulonephritis characterized by C3 accumulation with little or absent deposition of immunoglobulin, in the absence of ultrastructural electron-dense transformation seen in dense deposit disease.
Homologues: Orthologues: chimpanzee CFI (98% identical), macaque CFI (83% identical), rabbit CFI (75% identical), pig CFI (75% identical), rat Cfi (71% identical), dog CFI (70% identical), mouse Cfi (70% identical), guinea pig CFI (70% identical), tropical clawed frog cfi (52% identical), Drosophila melanogaster CG31267 (11% identical), Drosophila melanogaster CG31266 (11% identical). Paralogues in human: F11 (20% identical), KLKB1 (20% identical), F12 (20% identical), F10 (20% identical), F9 (19% identical), F7 (19% identical), HGFAC (19% identical), C1R (18% identical), C1S (18% identical), C1RL (14% identical), PRSS55 (14% identical), HP (11% identical), and 4 more.
Diseases named in the same sentence as CFI in open-access papers:
CFI is named in the same sentence as 105 diseases in open-access papers, as found by Europe PMC text mining. Sharing a sentence is not in itself a finding about the gene and the disease. The quoted sentences say what the papers report.
age-related macular degeneration (29 papers, 2012 to 2026). Age-related loss of vision in the central portion of the retina (macula), secondary to retinal degeneration. "We have also characterized complement factor H (CFH) and CFI variants identified in patients with age-related macular degeneration (AMD), a leading cause of blindness in the developed world." (PMID 34912830, 2021). "Genetic variants in the CFH and CFI genes that lead to haploinsufficiency (i.e., ~50% reductions in the levels of FH and FI) have been associated with age-related macular degeneration (AMD)." (PMID 32064578, 2020). "Genetic variation in complement factor I (CFI) leading to reduced FI levels or impaired FI function has been associated with diseases such as age-related macular degeneration (AMD) and atypical hemolytic uremic syndrome (aHUS)." (PMID 35069568, 2021). "Variants in the CFI gene have been linked to age-related macular degeneration (AMD), chronic infection, and broader aging processes." (PMID 34718232, 2021). "Rare genetic variants in complement factor I (CFI) that cause low systemic levels of the protein (FI) have been reported as a strong risk factor for advanced age-related macular degeneration (AMD)." (PMID 32516404, 2020). "A recent study among patients with intermediate age-related macular degeneration demonstrated higher levels of complement factor B and complement factor I in females as compared to males." (PMID 38385704, 2024). "Rare variants (RVs) in the gene encoding the regulatory enzyme complement factor I (CFI; FI) that reduce protein function or levels increase age-related macular degeneration risk." (PMID 38852887, 2024). "Advanced age-related macular degeneration (AAMD) risk is associated with rare complement Factor I (FI) genetic variants associated with low FI protein levels (termed ‘Type 1’), but it is unclear how variant prevalences differ between AMD patients from different ethnicities." (PMID 36067162, 2022). "To evaluate potential diagnostic and therapeutic biomarkers for age-related macular degeneration (AMD), we identified 8433 UK Biobank participants with rare complement Factor I gene (CFI) variants, 579 with optical coherence tomography-derived macular thickness data." (PMID 35285476, 2022). "Although the inflammation in AMD is largely mediated through complement-associated pathways, such as CFH, CFI, C2, CFB, and C3, other mechanisms have also been reported, including age-related maculopathy susceptibility (ARMS2), which acts through a matrix metalloproteinase inhibitor." (PMID 36011777, 2022). "Therefore, we conducted for the first time in a sample of the Algerian population a replication study to analyse the frequency of CFI rs10033900 and ARMS2 rs3750846 polymorphisms and to evaluate the effect of these two polymorphisms on exudative age related macular degeneration." (PMID 36059931, 2022). "Complement factor I (FI) is a central inhibitor of the complement system, and impaired FI function increases complement activation, contributing to diseases such as age-related macular degeneration (AMD) and atypical hemolytic uremic syndrome (aHUS)." (PMID 35069568, 2021). "The update of June 2006 included mutations for CFI and MCP alongside structural models for their domains, and also included SNPs (single nucleotide polymorphisms) for these three proteins that show disease-risk associations for conditions such as age-related macular degeneration." (PMID 25188723, 2014). "Complement factor I (CFI), another protein of the complement systems, is also involved in age-related macular degeneration." (PMID 23936146, 2013). "In genetic studies on age-related macular degeneration (AMD), its association with the CFH gene led to the discovery that other molecules in the complement pathway were also associated with the condition, such as C2/CFB, C3, and CFI." (PMID 23213273, 2012).
age-related macular degeneration (continued). "The pathology of age-related macular degeneration (AMD) is suggested to be influenced by polymorphisms and/or substantially altered expression levels of complement factors, including complement factor B (CFB) and complement factor I (CFI), both of which are serine proteases." (PMID 31398819, 2019). "To assess a potential diagnostic and therapeutic biomarker for age-related macular degeneration (AMD), we sequenced the complement factor I gene (CFI) in 2266 individuals with AMD and 1400 without, identifying 231 individuals with rare genetic variants." (PMID 25788521, 2015).
atypical hemolytic-uremic syndrome (12 papers, 2011 to 2025). "Approximately 60% of cases of atypical hemolytic uremic syndrome are associated with deficiencies of the complement regulatory protein, including mutations in complement factor H, complement factor I, or the membrane co-factor protein." (PMID 35241161, 2022). "The FI-mediated regulatory mechanisms are also associated with CFI variants determinant in atypical hemolytic uremic syndrome and systemic lupus erythematosus." (PMID 32610682, 2020). "Five of these patients had risk variants in MCP or CFI that were previously identified in atypical hemolytic uremic syndrome, a disease characterized by endothelial damage." (PMID 21445332, 2011). "Genetic analyses identify rare variants in complement regulators (CFH, CFI, MCP) and proteins (C5, C6), suggesting a shared mechanism between preeclampsia and complement-mediated disorders like atypical hemolytic uremic syndrome (aHUS)." (PMID 40777009, 2025). "Other mutations in genes encoding C3, complement Factor I (CFI), CFB, factors related to CFH, CFHR1–5 and CD46 (MCP) have been associated with C3G, as already described in atypical hemolytic-uremic syndrome." (PMID 32478016, 2020).
geographic atrophy (8 papers, 2017 to 2025). "This study demonstrates, for the first time, the prevalence of disease‐causing complement factor I (CFI) gene mutations in an unselected cohort of patients with geographic atrophy secondary to age‐related macular degeneration." (PMID 34153144, 2021). "No studies have been undertaken on the prevalence of disease‐causing CFI mutations in patients with geographic atrophy (GA) secondary to AMD." (PMID 34153144, 2021). "In particular, Lampalizumab (FCFD4514S) has been shown to reduce the geographic atrophy enlargement in phase II trials of dry AMD in patients who also have a CFI polymorphism, indicating that inhibition of complement is a promising approach." (PMID 28913923, 2017). "Complement-modulating gene therapies, such as AAV-based delivery of complement factor I for geographic atrophy, were designed to restore homeostatic regulation of the complement cascade through long-term local expression." (PMID 41532047, 2025). "GT005, an AAV2-based complement factor I gene therapy for geographic atrophy, was discontinued in 2023." (PMID 41532047, 2025). "Clinical trials targeting proteins encoded by the AMD-associated genomic loci C3, CFB, CFI, CFH, and ARMS2/HTRA1 are currently ongoing, and a phase III clinical trial for C3 inhibition recently showed a modest reduction of lesion growth in geographic atrophy." (PMID 36108770, 2022). "In the MAHALO phase 2 trial (Genentech) in geographic atrophy, the CFD inhibitor, lampalizumab, slowed disease progression most prominently in individuals with a particular genetic makeup which notably linked to a polymorphism in the CFI gene." (PMID 28986638, 2018).
systemic lupus erythematosus (7 papers, 2014 to 2025). An autoimmune multi-organ disease typically associated with vasculopathy and autoantibody production. "Three patients with LN combined with renal TMA have mutation in CFI and CFHR2 genes responsible for complement regulation; this is consistent with previous findings in adult lupus patients." (PMID 33614676, 2020). "Mutations of complement regulatory proteins including membrane cofactor protein, complement factor I, and complement factor H have also been observed in patients with systemic lupus erythematosus (SLE) and antiphospholipid antibody positivity." (PMID 25474424, 2014).
thrombotic microangiopathy (6 papers, 2018 to 2025). The syndromes of microangiopathic hemolytic anemia, thrombocytopenia, and variable signs of organ impairment, due to platelet aggregation in the microcirculation. "The I416L variant of complement factor I is associated with thrombotic microangiopathy among patients of African ancestry." (PMID 40600167, 2025).
glomerulonephritis (5 papers, 2011 to 2021). A renal disorder characterized by damage in the glomeruli. "Defects in CFI cause multiple complement-related diseases, including aHUS and CFI deficiency (OMIM: 610984), a disease characterized by recurrent infections and glomerulonephritis in some patients." (PMID 23251215, 2012). "For example, CFI deficiency can cause C3GN in humans, whereas CFI knockout does not cause spontaneous glomerulonephritis and proteinuria, but does result in mesangial C3 deposition and expansion in a portion of the knockout mice." (PMID 34149444, 2021). "In conclusion, glomerulonephritis diseases, particularly those that coexist with isolated C3 glomerulonephritis and aHUS, may be associated with CFH, complement factor I, and MCP mutations." (PMID 27460033, 2016).
breast carcinoma (4 papers, 2019 to 2025). "On the other hand, elevated expression levels of CFI have been reported to correlate with tumor invasiveness and poor prognosis in cSCC, breast cancer, and glioma." (PMID 40283026, 2025).
Hypertension (4 papers, 2019 to 2022). The presence of chronic increased pressure in the systemic arterial system. "Moreover, DisGeNET analysis results demonstrated remarkable changes were caused by SLC39A1 in genes associated with complement Factor I (C3 inactivator) deficiency, ischemic stroke, choriocarcinoma and hypertensive disease." (PMID 36407113, 2022). "It is possible that specific environmental and lifestyle factors alter the associations between CFI polymorphisms and AMD, including age, diabetes, smoking, familial history and hypertension." (PMID 32215612, 2020).
macular degeneration (4 papers, 2020 to 2025). Loss of vision in the central portion of the retina (macula), secondary to retinal degeneration. "Further major complement risk alleles in macular degeneration include C2-CFB, CFI, C3 and TIMP328,33." (PMID 36316518, 2022).
periodontitis (4 papers, 2023 to 2026). An acute or chronic inflammatory process that affects the tissues that surround and support the teeth. "Then, it was discovered that CFI, DDIT4L, and FAM46C are useful diagnostic markers for periodontitis and MS." (PMID 38218802, 2024). "LASSO analysis indicated that CFI, DDIT4L, and FAM46C were the most effective shared diagnostic biomarkers for periodontitis and MS, which were further validated by qPCR and immunohistochemical staining." (PMID 38218802, 2024). "Three overlapping genes (FAM46C, CFI, and DDIT4L) were identified as the most effective diagnostic biomarkers for both periodontitis and MS by using a Venn diagram." (PMID 38218802, 2024). "Results of our study discovered that the most significant crosstalk genes between periodontitis and MS were FAM46C, SLC7A7, LY96, CFI, DDIT4L, CD14, and IGJ, which may be associated with response to molecules of bacterial origin." (PMID 38218802, 2024). "Venn diagrams revealed that there were eight shared genes (FAM46C, SLC7A7, LY96, CFI, DDIT4L, CD14, C5AR1, and IGJ) that overlapped between periodontitis and MS which were screened by WGCNA and DEGs." (PMID 38218802, 2024). "Results of immunohistochemical staining revealed that CFI, DDIT4L, and FAM46C were upregulated in periodontitis samples compared with healthy controls." (PMID 38218802, 2024). "qRT-PCR results indicated that mRNA levels of the pro-inflammatory cytokines (IL-1, IL-6, and IL-8) and also CFI, DDIT4L, F4AM6C were upregulated in patients with periodontitis compared with healthy controls." (PMID 38218802, 2024). "Further studies found that three candidate biomarkers (FAM46C, CFI, and DDIT4L) expression levels were all upregulated in both periodontitis and MS samples." (PMID 38218802, 2024). "Further studies found that CFI, DDIT4L, and FAM46C were potential biomarkers in periodontitis and MS." (PMID 38218802, 2024). "The expression trends of CFI (upregulated) and COQ2 (downregulated) were first confirmed in TNF-α/IL-1β-stimulated human periodontal ligament cells and further validated in a rat ligature-induced periodontitis model." (PMID 41998822, 2026).
vasculitis (4 papers, 2018 to 2025). "We report a case of disseminated gonococcal infection linked to complement factor I (FI) deficiency, with a prior vasculitis-like episode." (PMID 41607490, 2025). "Heterozygous GOF mutations in C3 are now added to the list of genetic complement deficiencies causing vasculitis such as C1q, C1r, and C1s deficiency, complement factor I deficiency and complement C2 and C4 deficiency." (PMID 30443255, 2018). "CFI deficiency is thus now added to the growing list of monogenic causes of vasculitis and should always be considered in vasculitis patients found to have persistently low levels of C3 with normal C4." (PMID 29696024, 2018). "In summary, the present study together with the previous one suggests that mast cells are a marked source for C3 and C3b that is further cleaved by accumulating CFI+ cells to iC3b in the early vasculitis lesion." (PMID 35747245, 2022).
Alzheimer disease (3 papers, 2018 to 2021). A progressive, neurodegenerative disease characterized by loss of function and death of nerve cells in several areas of the brain leading to loss of cognitive function such as memory and language. "CFI-mediated complement regulation was reported to be involved in the progression of Alzheimer’s disease." (PMID 35010640, 2021).
IgA nephropathy (3 papers, 2018 to 2023). "Moreover, higher transcripts of CD46, CD55, CD59, and CFI were observed in recurrent IgAN nephropathy than in native kidney IgA nephropathy." (PMID 30356754, 2018).
lupus nephritis (3 papers, 2018 to 2024). Glomerulonephritis in the context of systemic lupus erythematosus. "Urinary complement biomarkers, particularly urinary C3d, C4, CFI and C5b-9 have shown promise as reliable tests to identify active lupus nephritis, monitor disease activity, assess treatment response, and predict disease flare in a few studies." (PMID 38895123, 2024). "In contrary to pervious study which analyzed the correlation of serum CFH and disease activity of patients with lupus nephritis, our study demonstrated that only serum CFI but not CFH and CD46 correlated statistically with SLEDAI scores." (PMID 29492211, 2018). "This study highlights the importance of looking at the balance between complement activation (e.g., MAC complex) and regulation (e.g. CD 59) in evaluating complement biomarkers and suggests C3, CFI and C9-to-CD59 ratio may be a marker of tubulointerstitial disease in lupus nephritis." (PMID 38895123, 2024).